CXCR6 (C-X-C motif chemokine receptor 6)
Diseases named in the same sentence as CXCR6 in open-access papers (continued):
Sharing a sentence is not in itself a finding about the gene and the disease.
infection (continued). "Viral DNA levels were unchanged in the spleen over the course of infection, indicating that loss of CXCR6 did not result in a global defect in virus control." (PMID 40043065, 2025). "Indeed, the inhibition of CXCR6 can progressively better the infection of PJI over time, indicating the reactivation of antibacterial immunity." (PMID 39716908, 2025). "CXCR4 and CXCR6 individually regulate the migration of T cells in this infection model." (PMID 40581668, 2025). "Around half of CD4 T cells expressed both CD69 and CXCR6 beyond 4 weeks post infection." (PMID 40060443, 2025). "Expression of effector molecules was detected in CXCR6+ CD8 T cells after resolved infection, such as Gzmb, Cxcr3, Ccr2 and Ccr5, in contrast to enriched expression of co-inhibitory receptors by CXCR6+ CD8 T cells during persistent hepatic infection, such as Pdcd1 and Lag3." (PMID 38987588, 2024). "In LCMV clone 13 infection, one TRM cell cluster expressing PD-1, CD38, CD39, CD54, and CXCR6 significantly associated with the liver, whereas a TEM cell subset of cells expressing high levels of PD-1, CX3CR1, NKG2A, and Ly6C (Cl13 cluster 5) was more abundant in the lungs and spleen." (PMID 33458613, 2021). "Here, we report that infection by Trypanosoma brucei induced depletion of macrophages in the liver, leading to the repopulation of CXCL16-secreting intrahepatic macrophages, associated with substantial accumulation of CXCR6+CD4+ T cells in the liver." (PMID 34614031, 2021). "Interestingly, however, CXCR6 had a significant role in maintaining MAIT cells in the airway lumen long after clearance of LVS infection." (PMID 32849637, 2020). "However, CXCR6 does contribute to long-term retention of MAIT cells in the airway lumen after clearance of the infection." (PMID 32849637, 2020). "Adoptive transfer of CXCR6-deficient and WT P25-specific CD4+ T-lymphocytes showed an increase of CXCR6-deficient cells in the lungs and BAL at day 7 after PR8-P25 infection, but by day 20 equivalent numbers of WT and CXCR6-deficient cells were present at all sites." (PMID 30899256, 2019). "The role for CXCR6 during infection, however, is less clear." (PMID 30899256, 2019). "It is thus tempting to speculate that use of CXCR6, combined with highly restricted CCR5 expression in natural hosts, would direct SIV to cell types that are more easily replenished and whose infection and loss are less likely to disrupt immune homeostasis." (PMID 29659623, 2018). "Thus, the intriguing association between targeting CXCR6/CCR5 versus CCR5-only CD4+ T cell subsets and pathogenic infection outcomes in the HIV-1/SIVcpz/SIVmus/gsn/mon lineage requires further study." (PMID 29659623, 2018). "Similarly, chemokine CXC ligand 12 (CXCL12) and chemokine (CXC motif) receptor 6 (CXCR6) were upregulated by infection in CHB." (PMID 27197554, 2016). "The decrease in intracellular IFNγ production by CD3+ lymphocytes in this infection model could be related to impaired activation of CXCR6+ iNKT cells since Salmonella typhimurium glycolipids are known to stimulate iNKT cell responses." (PMID 27471636, 2016). "Interestingly, we observed impaired hepatic accumulation of CXCR6-deficient CD8+ T cells at early time points after transfer and infection which mainly affected CD8+ T cells with a highly activated CD44+CD62L−KLRG1+ phenotype." (PMID 24832098, 2014). "Thus, CXCR6 appears to play a role in the early phase of infection but is subsequently replaced by other chemokine receptors or chemokine independent mechanisms of T cell recruitment up-regulated with ongoing infection." (PMID 24832098, 2014). "In our studies, CCR5, CCR10 and CXCR6 were slightly up-regulated at the early infection." (PMID 21819625, 2011).
infection (continued). "We therefore investigated whether the intranasal or intramuscular infection with NY-ESO-1 S-FLU virus differentially induced the expression of the molecules (VLA-1 [CD49a], CXCR6, CD103, CD44, CD49d, CCR5 and CXCR3) implicated in retention or trafficking of effector CD8+ T cells in lung." (PMID 36626205, 2023). "Importantly, CXCL16, the ligand for CXCR6, is upregulated in normal tissues following infection so all CXCR6-expressing T cells may be recruited to the site along with specific T cells." (PMID 33968757, 2021). "At 5 dpi, when all three populations of interest had formed, we sorted P14 cells from the three branches according to expression of CXCR6 and TCF1 (detected by GFP) and transferred them into infection-matched hosts." (PMID 40971956, 2025). "By 4-weeks post-infection and treatment, PbTII cells and polyclonal CD4+ T cells exhibit GC Tfh (PD1hi CXCR5hi), Tfh/TCM-like (CXCR5+ PD1lo) or Th1-TEM (CXCR5lo CXCR6+) memory phenotypes in the spleen." (PMID 40132035, 2025). "Second, S. aureus burden and biofilm formation surrounding the prostheses were assessed at 7d and 35d post infection in both PJI mice and CXCR6‐KO PJI mice." (PMID 39716908, 2025). "Both CXCR6+ CD8 T cells and CX3CR1+ CD8 T cells from the liver and spleen after resolved infection efficiently eliminated target cells and produced interferon-γ (IFNγ) and tumour necrosis factor (TNF) ex vivo after cognate stimulation." (PMID 38987588, 2024). "By day 14 post-infection, granzymes A and B were upregulated in Mamu-B*08+ RMs, as well as CXCL6 and CXCR6." (PMID 39502699, 2024). "We proceeded to characterize CD8 T cells present in RPE/c and neural retinas on day 8 after infection using markers typically responsible for endothelial adhesion (LFA-1), retention in tissues (CD69) and migration/positioning (CXCR6, CXCR3)." (PMID 37662932, 2023). "Studies on immune surveillance in organs such as the liver and lungs have shown that the chemokine receptor CXCR6 and its ligand CXCL16 are important for migration of CD8 T cells in the tissue during an infection in mice." (PMID 37662932, 2023). "In patients with moderate infection, CD8+ TRM cells alleviate inflammation through CXCR6-mediated virus clearance, while the expression of CD8+ TRM cells is unstable and reduced in patients with severe infection, leading to viral replication." (PMID 36032142, 2022). "Another gene involved is C-X-C motif chemokine receptor 6 (CXCR6), whose function is to allow homing of CD8+ T cells in the lungs, as occurs during infection by the influenza virus." (PMID 35062298, 2022). "On the third day after infection, CXCR3+CXCR6+ γδT cells showed significantly higher expression of Ki67, indicating that the proliferative capacity of CXCR3+CXCR6+ γδT cells was enhanced postinfection." (PMID 35126348, 2021). "Upon MCMV-GP33 infection, two TRM cell clusters expressing CD38, CD11a, CD11c, CXCR6, and Sca-1, typified by divergent KLRG1 expression, connected uniquely to the liver." (PMID 33458613, 2021). "Although we were unable to detect a difference in the number of MAIT cells present in the lungs of WT and CXCR6−/− mice after LVS IN infection, it was possible that the MAIT cells accumulating in the lungs of the CXCR6−/− mice had functional deficits." (PMID 32849637, 2020). "Upregulation of ICOS, CXCR3, CXCR6, IL-18R1, and Chil3 in the brains of T. gondii-infected SCID mice that received a transfer of CD8+ immune T cells at 6 weeks after infection." (PMID 32291349, 2020). "To further elucidate the role of CXCR6 in MAIT cell localization and function during infection, we compared MAIT cell accumulation in the lungs of CXCR6 knock out mice (CXCR6−/−) and WT mice after LVS IN infection." (PMID 32849637, 2020). "For example, the expression of CFI, CXCR6, LGALS15, and MMP1 was significantly upregulated while TFF2 mRNA level was significantly repressed by infection only in the resistant breed (CHB), in a good agreement with the RNAseq analysis." (PMID 27197554, 2016).
infection (continued). "Splenic CD4+ YFP+ GFP+ T cells from mice on day 7 of infection were almost universally CXCR3+, whereas they expressed only low levels of CCR1, CCR6, and CXCR6." (PMID 26459508, 2016). "In general, the percentage of CCR2, CCR5, CXCR6 and CD11c (Itgax) in live CD4+ or CD4- (putative CD8+) T cells peaked 10 days after infection, when in most cases their total frequency was significantly higher than in the control group." (PMID 27272720, 2016). "Our results showed that the majority of chemokines and receptors were up-regulated more strongly in the CVS-11 infection than the HEP-Flury at a later stage, besides CCL22, CXCR3, CXCR6, and CCR7." (PMID 27242764, 2016). "It has been shown that inflammatory chemokine receptors, such as CXCR3, CXCR6, and CCR5, are upregulated during infection." (PMID 26322025, 2015). "After infection of mice with L. monocytogenes, CD8+ T cells from spleen and liver showed up-regulation of CXCR6." (PMID 24832098, 2014). "We therefore tested the ability of SIVsmm envelopes to mediate infection through human CCR2b, CCR3, CCR8, GPR1, GPR15 (BOB), CXCR6 and CXCR4." (PMID 20865163, 2010). "Absence of CXCR6 did not affect the level of infection or CD4+ or virus-specific CD8+ T cell numbers in the brain." (PMID 40581668, 2025). "Although targeting CXCR6 alone is not sufficient to clear the infection, it significantly impedes the progression of S. aureus PJI." (PMID 39716908, 2025). "Contemporary SIVmus, similarly to SIVsmm and SIVagm, uses both CCR5 and CXCR6 for cell entry, suggesting the CXCR6 usage as a major coreceptor is attributable to SIVs with nonpathogenic course of infection in their respective hosts MUS, SM, and AGM." (PMID 35154162, 2022). "From the results, we observed that most of the chemotactic factors (e.g., CCR5, CXCR6, and CCL5), which are pivotal mediators of host defense and orchestrate the recruitment of immune cells into sites of infection and inflammation, were significantly up-regulated in the IMMUNITY_H samples." (PMID 35359451, 2022). "MAIT cells are predominantly CXCR6+ but do not require CXCR6 for accumulation in lungs after an infection." (PMID 36311728, 2022). "Our data also indicates that lack of CXCR6 gene enhances disease severity, implicating a role in protecting against lethal infection as well." (PMID 35862771, 2022). "In the liver, we found a population of TRM cells expressing CD223 (LAG-3), CXCR6, and CD43 as well as high CD39 and PD-1 levels to represent more than 70% of the total liver antigen-specific CD8+ T cells upon chronic LCMV clone 13 infection." (PMID 33458613, 2021). "The percentage of CXCR6+ cells in the peripheral blood is much lower in mice with no history of infection, but is upregulated following infection." (PMID 33968757, 2021). "Although our data show that CXCR6 is not required to increase MAIT cell numbers in the lungs during the peak of infection, this does not rule out a redundant role for the CXCR6/CXCL16 axis in MAIT cell accumulation." (PMID 32849637, 2020). "Although our data showed that CXCR6 was not essential for MAIT cell recruitment during LVS infection, this does not rule out a non-redundant role for the CCR6/CXCL16 axis in MAIT cell accumulation." (PMID 32849637, 2020). "Overall, our data show that CXCR6 is not required for MAIT cell recruitment during infection but instead supports long-term retention of MAIT cells in the airway lumen." (PMID 32849637, 2020). "While MUS lymphocytes were not available to test primary cell infection using a CXCR6 blocking agent, as was done in our SM and AGM studies, our results nevertheless identify another distinct SIV lineage that appears to share this entry pathway." (PMID 29659623, 2018). "SIVagmVer, which infects vervet AGMs, has also been shown to not require CCR5 for primary cell infection ex vivo, and to use CXCR6 efficiently in vitro." (PMID 29659623, 2018).
infection (continued). "Thus, efficient use of CXCR6, instead of or in addition to CCR5, appears to be a common feature of virus/host interactions in multiple natural host infections, where CCR5 expression is low or, in some cases, genetically absent." (PMID 29659623, 2018). "Similarly, upregulation of IFNγ or CXCR6 upon re-infection proceeded normally in the absence of Myo1f (Fig 7Ci-ii)." (PMID 40132035, 2025). "CXCR6 is thus not essential for migration of CD4+ TIA cells to the site of infection." (PMID 38838013, 2024). "Our observation that efficient CXCR6-mediated entry is a common feature of SIVsmm, SIVagm and now SIVmus infections suggests that use of this pathway may enable robust replication in the face of limited CCR5." (PMID 29659623, 2018). "In contrast, expression of CXCR6 (the receptor for CXCL16) mRNA was not affected by Ct infection." (PMID 28515460, 2017). "Thus, control of listeria-infection occurred independent of CXCR6 and in the liver, absence of CXCR6 even improved clearance of bacteria." (PMID 24832098, 2014). "Thus, CXCR6 and GPR15 are particularly likely candidates for mediating SM infection independent of CCR5, and further studies are required to determine which one or ones are responsible for entry into primary SM PBMC ex vivo and infection in vivo." (PMID 20865163, 2010). "Of note, both CXCR6 and GPR15 are also highly expressed in intestinal tissues, raising the question of whether alternative coreceptor use may be involved in mucosal events that play a central role in infection." (PMID 20865163, 2010). "However, the most recent research has reported that MAIT cells could largely proliferate in situ in the infection organ but do not require CXCR6 for accumulation." (PMID 34321090, 2021). "Thus the low HIV-2 reservoirs differ from HIV-1 reservoirs by the lack of monocytic infection and a limited infection of TCM associated to a lower expression of a potential alternative HIV-2 co-receptor, CXCR6 and a higher expression of a restriction factor, TRIM5." (PMID 31095640, 2019). "Studies of humans and mice show that CXCR6 expression is restricted to extralymphoid sites, and if true for monkeys naturally infected with SIV, could enable viral replication while avoiding lymphoid tissue infection that leads to inflammation, fibrosis and damage seen in pathogenic infections." (PMID 29659623, 2018). "CXCL12 and CXCL16 are expressed by the ependyma and periventricular region irrespective of infection, paralleling the expression of CXCR4 and CXCR6 by brain-infiltrating T cells to regulate their migration to infectious foci to the ventricular barrier." (PMID 40581668, 2025). "Second, complementing the ΔVpr virus with Vpr in trans allowed for Vpr packaging into virions and delivery into cells without de novo Vpr synthesis during infection, and fully rescued upregulation of CD69 and CXCR6 spinoculation of resting CD4+ T cells." (PMID 35417711, 2022). "After infection with WNV, Cxcr6−/− mice exhibit a similar frequency of virus-specific CD8+ T cells as WT mice in the forebrain, indicating no role for CXCR6 in T cell recruitment at peak CNS viral loads." (PMID 36153630, 2022). "A small but significant increase in the levels of CXCR6-expressing MAIT cells was also observed in the spleen, but not the thymus and LP after infection." (PMID 32849637, 2020). "Using this infection model, we find that MAIT cells are predominantly CXCR6+ but do not require CXCR6 for accumulation in the lungs." (PMID 32849637, 2020). "Nevertheless, the only known ligand for CXCR6, CXCL16, is sufficient to drive MAIT cell accumulation in the lungs in the absence of infection when administered in combination with the MAIT cell antigen 5-OP-RU." (PMID 32849637, 2020). "Here we find that, despite being predominantly CXCR6+, MAIT cells do not require CXCR6 for accumulation at the site of infection." (PMID 32849637, 2020).
infection (continued). "Strikingly, responding Ki67+ CD56bright NK cells expressed higher levels of CLA, CCR5, CXCR6, and CCR9 as compared to both non-responding NK cells during the acute phase of infection as well as healthy controls." (PMID 31467285, 2019). "More recently, we showed that both SIVsmm and SIVagmSab infections did not require CCR5 in vivo and/or ex vivo and efficiently used CXCR6 in addition to CCR5." (PMID 29659623, 2018). "Overall, these data show that CXCR6 is not essential for MAIT cell accumulation in the lungs and spleen during LVS IN infection but has a significant role in maintaining MAIT cells in the airway lumen long after clearance of the infection." (PMID 32849637, 2020). "However, MAIT cell numbers in the airway lumen, but not the lung parenchyma, were significantly reduced in CXCR6−/−mice as compared to WT mice on day 54, long after clearance of the LVS infection (at approximately day 18)." (PMID 32849637, 2020). "This implies that in the absence of CXCR6 expression, CD4+ T-lymphocytes may be recruited to the lungs earlier or potentially undergo a greater degree of proliferation at the site of infection." (PMID 30899256, 2019). "Nevertheless, CXCR6 was highly expressed in CD4+ TIA cells from memory mice but also in NKG2D+CD4+CD44+ T cells from control mice, which could be stimulated to produce IFN-γ in vitro, but were not recruited to the site of infection in vivo, hinting toward alternative recruitment mechanisms." (PMID 38838013, 2024).
bacterial infection (3 papers, 2016 to 2021). "Although early studies implicate CXCR6 in recruitment of natural killer T cells and T cells to various autoimmune sites, CXCR6 is also important for the recruitment of CD8 T cells in response to viral and bacterial infections." (PMID 34362825, 2021). "We propose that CCR6+, CXCR6+ and αEβ7-expressing intrahepatic MAIT cells are retained close to the bile ducts in steady state to provide protection against ascending bacterial infection from the gut." (PMID 26743076, 2016).
kidney diseases (3 papers, 2018 to 2025). "These receptors, as well as CCR6 and CXCR6, are also involved in T cell recruitment to the kidney during renal disease." (PMID 29868028, 2018).
inflammation (2 papers, 2019 to 2024). Aberrant reaction of the microcirculation characterized by movement of fluid and leukocytes from the blood into extravascular tissues. "It appears that the recruitment of NK cells in case of lung inflammation might be indirectly dependent on CXCR6 expression by T or B lymphocytes." (PMID 31690060, 2019). "It appears that the recruitment of NK cells in case of lung inflammation might be indirectly dependent on CXCR6 expression by lymphocytes." (PMID 31690060, 2019). "Current studies have shown that both CXCR6 and CD69 are highly expressed in intestinal resident memory T cells (TRM), which is crucial for the induction of IBD-related chronic inflammation." (PMID 38243324, 2024).
neurodegenerative disease (2 papers, 2022 to 2024). A disorder of the central nervous system characterized by gradual and progressive loss of neural tissue and neurologic function. "The CXCL16/CXCR6 chemokine signaling pathway may also be an important target for other neurological and neurodegenerative diseases that are associated with neuroinflammation in the CNS." (PMID 36153630, 2022). "In other words, the CXCL16/CXCR6 pathway between T cells and microglia may be an important target for the treatment of other neurological diseases and neurodegenerative diseases related to neuroinflammation in the central nervous system." (PMID 39440247, 2024).
respiratory diseases (2 papers, 2021 to 2023). "In particular, CXCR6, which is prominently expressed in T lymphocytes, NK, and NKT cells, has been shown to be involved in the recruitment of immune cells to non-lymphoid organs in chronic inflammatory and respiratory diseases." (PMID 37762093, 2023).
infectious disease (1 paper, 2021). A disorder directly resulting from the presence and activity of a microbial, viral, or parasitic agent in humans. "While a role for CXCR6 in CD8+ Trm responses using infectious disease models has been reported, to date, there are no reports on the functional role of CXCR6 in mediating Trm responses to tumors." (PMID 34607898, 2021).